MMP9 (matrix metallopeptidase 9)
Diseases named in the same sentence as MMP9 in open-access papers (continued):
Sharing a sentence is not in itself a finding about the gene and the disease.
rosacea (23 papers, 2010 to 2026). A chronic erythematous skin disorder that affects the face. "MMP2 and MMP9 are associated with the pathogenesis of rosacea, with elevated MMP-9 mRNA levels in rosacea patients’ facial skin." (PMID 39351216, 2024). "In rosacea patients, increased IL-17 levels are associated with inflammation, angiogenesis, and the stimulation of LL-37 and MMP-9 expression." (PMID 38201332, 2023). "Finally, we analyzed the ROC curve (receiver operating characteristic curve) for MMP-9 in the GCF to determine the diagnostic accuracy of rosacea." (PMID 36077255, 2022). "The analysis showed that patients with rosacea had significantly higher levels of MMP-9 compared with controls (764.52 ± 569.83 pg/mL vs. 260.69 ± 170.43 pg/mL, p < 0.05)." (PMID 41373451, 2025). "Mast cells are known to contribute to rosacea pathophysiology by releasing histamine, matrix metalloproteinases such as MMP9, and various pro-inflammatory cytokines in response to LL-37 stimulation." (PMID 40725084, 2025). "In this LL-37-induced rosacea-like model, the mRNA expression of several key mediators including Mmp9 and Vegfa was markedly upregulated." (PMID 40725084, 2025). "The level of MMP9 expression is significantly increased in the lesions and serum of rosacea patients." (PMID 38321132, 2024). "It has been demonstrated that MMP9 expression and M0 macrophage infiltration were significantly increased in both rosacea and acne lesions, which is consistent with our results." (PMID 38321132, 2024). "And notably, MMP9 was significantly positively correlated with M0 macrophages in both rosacea and acne lesions (R > 0.75, P-value < 0.01)." (PMID 38321132, 2024). "Higher levels of MMP-9 mRNA have been detected in facial skin samples from rosacea patients compared to the facial skin of healthy subjects, suggesting that MMP-9 is involved in the development of rosacea." (PMID 36077255, 2022). "The Area under ROC for MMP-9 was 0.869 (95%, C.I: 0.719–0.956), with a sensitivity of 72.22% and specificity of 81.58% for the diagnosis of rosacea." (PMID 36077255, 2022). "This manuscript aims to compare the GCF levels of MMP-2 and MMP-9 in systemically healthy and rosacea patients and to evaluate their potential use as novel disease biomarkers." (PMID 36077255, 2022). "The Area under ROC for MMP-9 was 0.869 (95%, C.I: 0.719–0.956), with a sensitivity of 72.22% and specificity of 90.5% for the diagnosis of rosacea." (PMID 36077255, 2022). "Analysis showed mean and standard deviation of MMP-9 concentrations in the GCF for patients with rosacea was 764.52 ± 569.83 pg/mL; for healthy patients, it was 260.69 ± 170.43 pg/mL (p < 0.05)." (PMID 36077255, 2022). "In the present study, we report higher levels of MMP-9 in the GCF of patients with rosacea compared to systemically healthy controls." (PMID 36077255, 2022). "Therefore, MMP-9 in the GCF could be a diagnostic biomarker for rosacea." (PMID 36077255, 2022). "Today, no ROC curve areas are available for the tear and serum and the GCF levels of MMP-9 in rosacea diagnosis." (PMID 36077255, 2022). "Considering that the GCF is a non-invasive method and readily available biomarker source for systemic disease diagnosis, we evaluated if the detection of MMP-9 in the GCF serves as a biomarker of rosacea." (PMID 36077255, 2022). "Laboratory benchmark testing for this disease is not useful, therefore, we aimed to evaluate the gingival crevicular fluid (GCF) levels of extracellular metalloproteinases (MMP)-2 and MMP-9 as novel rosacea biomarkers." (PMID 36077255, 2022). "Higher levels of MMP-9 have been detected in tear fluid and serum, as well as pro-MMP9 in tears of patients with rosacea, compared to healthy patients, respectively." (PMID 36077255, 2022). "Tears of rosacea patients decreased after doxycycline treatment, suggesting the potential use of MMP-9 as a therapeutic biomarker for rosacea." (PMID 36077255, 2022).
rosacea (continued). "Despite these two studies available in the literature, more studies are needed to determine the role of MMP-9 at the local level in rosacea." (PMID 36077255, 2022). "In our study, we also found higher MMP-9 levels in the GCF of individuals with rosacea versus healthy controls, confirming that rosacea induces changes in biomarkers associated with the inflammation of this disease at a distance from the facial skin." (PMID 36077255, 2022). "In rosacea, when LL-37 is present, mast cells are partially responsible for changing the expression and activity of MMP-9." (PMID 36077255, 2022). "The mean and standard deviation of MMP-9 concentrations in the GCF for patients with rosacea was 764.52 ± 569.83 pg/mL; for healthy patients, it was 260.69 ± 170.43 pg/mL." (PMID 36077255, 2022). "Some studies have evaluated the expression of MMP-9 in rosacea; however its specific role is ascertained in this disease." (PMID 36077255, 2022). "MMPs are believed to be associated with the neurodegenerative diseases and an increased expression of MMP-1 and MMP-9 has also been observed in rosacea." (PMID 27649161, 2016). "The authors concluded that MMP-9 quantification in gingival crevicular fluid may serve as a reliable biomarker for rosacea, offering potential utility beyond conventional clinical assessment." (PMID 41373451, 2025). "Moreover, MMP9 was significantly positively correlated with M0 macrophages in both rosacea and acne lesions." (PMID 38321132, 2024). "Additionally, MMP9 mRNA, a key MC marker, is upregulated in rosacea-affected skin, primarily near blood vessels." (PMID 39351216, 2024). "Notably, MMP9 was significantly positively correlated with M0 macrophages in both rosacea and acne lesions in our study." (PMID 38321132, 2024). "In addition, we also found that there was a significant positive correlation between MMP9 and M0 macrophages in rosacea and acne lesions." (PMID 38321132, 2024). "Pharmacological inhibition of MMP9 reduces psoriasiform and rosacea-like dermatitis." (PMID 39385245, 2024). "Previous studies have shown that the expression of MMP2 and MMP9 is increased in rosacea skin." (PMID 39692542, 2024). "The GCF levels of MMP-9 were different between the rosacea and healthy control group." (PMID 36077255, 2022). "We suggest evaluating the ROC curve of MMP-9 in the GCF after rosacea treatment." (PMID 36077255, 2022). "Therefore, we suggest that the MMP-9 present in the facial skin of individuals with rosacea enters the circulation due to increased vascular permeability (provided by MMP-9 itself), driving it to the periodontal tissues." (PMID 36077255, 2022). "Interestingly, results from those studies indicate that rosacea has the potential to modify the concentrations of MMP-9 in these bodily fluids at a distance, hinting at a broader and “systemic” impact of the disease." (PMID 36077255, 2022). "However, we demonstrated that detecting MMP-9 in the GCF effectively diagnoses rosacea (ROC 0.8694)." (PMID 36077255, 2022). "Also, more studies are needed to elucidate the role of MMP-9 in the GCF of individuals with rosacea." (PMID 36077255, 2022). "Therefore, it is plausible that the elevated MMP-9 levels in the GCF of rosacea individuals cannot be explained by periodontal destruction." (PMID 36077255, 2022). "We performed a multiple linear regression model to elucidate whether the changes in the concentration of MMP-9 in the GCF of individuals with rosacea come from the periodontal tissue or rosacea." (PMID 36077255, 2022). "For example, MMP-9 in the skin of patients with rosacea might increase the levels of kallikrein 5 and LL-37, which are the key molecules in the pathophysiology of rosacea." (PMID 33670631, 2021). "MMP9 was reported as a key inflammatory factor and as a therapeutic target in both rosacea and AD." (PMID 34899707, 2021).
rosacea (continued). "Notably, some drugs with an MMP inhibitor function, such as doxycycline and tetracycline, were used for rosacea treatment, and the MMP9 inhibitor improved specific neurobehavioral deficits in AD mouse." (PMID 34899707, 2021). "Furthermore, following LL-37 injection in wild-type animals, murine mast cells were able to enhance the expression of IL-1, IL-6, and MMP-9, which have been known to augment inflammatory responses in rosacea." (PMID 27649161, 2016). "Therefore, we hypothesized that M0 macrophages may secrete MMP9 and act in concert with it to promote the development of inflammatory responses in rosacea and acne." (PMID 38321132, 2024). "MMP9 induces the production of pro-inflammatory cytokine, participates in angiogenesis, vasodilation, and tissue remodeling, which may make it the common hub gene in rosacea and acne." (PMID 38321132, 2024). "Finally, drug–target prediction and molecular docking revealed that AKT1/MAPK1/MMP9 could be the pharmacological targets of EGCG in rosacea." (PMID 36937834, 2023). "So, we speculated that EGCG could regulate autophagy by targeting ATK1, MAPK1, and MMP9 in rosacea." (PMID 36937834, 2023). "We conclude that the quantification of MMP-9 in the GCF could be used as a biomarker of rosacea." (PMID 36077255, 2022). "However, we propose to study the composition of the gingival microbiota in patients with rosacea and assess whether the presence or periodontal bacterial load influences the levels of MMP-9 in the GCF." (PMID 36077255, 2022). "Therefore, MMP-9 may be responsible for important features of rosacea, such as the development of permanent erythema and facial telangiectasias and the migration of inflammatory cells to affected facial skin." (PMID 36077255, 2022). "Notably, enhanced expression of MMP-2 and MMP-9 was observed in the skin of patients with rosacea." (PMID 27649161, 2016). "In rosacea, MMP-2 and MMP-9 are upregulated by UV light and inflammatory cytokines, promoting collagen breakdown and tissue remodeling." (PMID 41373451, 2025). "The expression of CXCL10, MMP9, IL1B, CXCL8, and CXCR4 were co-regulated by IRF1, STAT1, STAT3, IKBKB, HDAC1, ETS1, and CEBPB, which were highly expressed in rosacea and acne lesions." (PMID 38321132, 2024). "Also, detection of MMP-9 in GCF may be used as biomarker for rosacea diagnosis." (PMID 36077255, 2022). "Finally, the quantification of MMP-9 in the GCF could be used as a biomarker of rosacea." (PMID 36077255, 2022). "It was shown that MMP9 expression was increased in granulomatous rosacea lesions compared with non-granulomatous rosacea lesions." (PMID 41562711, 2025). "In addition, connective tissue hyperplasia in some rosacea patients is related to the persistence of inflammation, the activation of mast cells and the release of MMP1, MMP9, IL-6, and histamine, and the increased activity of the TRPs14." (PMID 38321132, 2024). "Few studies have assessed the expression of MMP-9 in facial skin samples of rosacea patients; nonetheless, several studies have explored its levels in other bodily fluids such as tears and serum." (PMID 36077255, 2022). "Unlike the evaluation of rosacea, the levels of MMP-9 at the periodontal and systemic levels have been widely evaluated." (PMID 36077255, 2022). "rosacea was responsible for increasing the levels of MMP-9 in the GCF independent of periodontal status." (PMID 36077255, 2022). "Moreover, studies demonstrated the potential relationship between MLT target genes (MMP9, CCND1, EGFR, ICAM1, PTGS2, and SERPINE1) and rosacea-related key genes (IL-6, IL-1β, IFNγ, IL-17, and TNF-α)." (PMID 34899707, 2021). "Moreover, MLT repressed the expression of proinflammatory cytokines, such as IL-6, TNF-α, TLR2, TGF-β1, MMP9, and VEGF in rosacea-like dermatitis." (PMID 34899707, 2021).
rosacea (continued). "In addition, the immunoexpression of MMP-9 in the dermis of rosacea Granulomatosa biopsies (advanced stage of rosacea) was higher than in rosacea non-Granulomatosa, suggesting that MMP-9 participates in the progression of rosacea." (PMID 36077255, 2022). "Also, rosacea was responsible for increasing the levels of MMP-9 in the GCF independent of periodontal status." (PMID 36077255, 2022). "The inhibition of LL37 could be a mechanism how both drugs improve the clinical features of rosacea such as erythema, telangiectasia and inflammation, since in a mouse model a LL37 injection led to such clinical features possibly through the enhanced expression of IL1, IL6 and MMP9 in mast cells." (PMID 40410272, 2025).
tuberculosis (23 papers, 2009 to 2023). A chronic, recurrent infection caused by the bacterium Mycobacterium tuberculosis. "Since the peripheral level of MMP-9 is associated with the severity of tuberculosis, IL-22 might also regulate MMP-9 expression to control MTB infection." (PMID 36839448, 2023). "Here, we further characterized the profile of those cytokines in clinical tuberculosis human and Mtb-infected model animal tissues and found that MMP-9 was highly expressed." (PMID 38235425, 2023). "MMPs, particularly MMP-9, have been reported to be expressed during various types of tuberculosis, including meningitis, active cavitary tuberculosis, and pleuritis." (PMID 36776550, 2022). "MMP-9 was found to be expressed in both osteoclasts, foreign body MNGCs, and disease-related MNGCs such as tuberculosis." (PMID 32514904, 2021). "MMP9 and Timp1 are known to be up-regulated in tuberculosis infection and have been proposed as biomarkers for diagnosis of tuberculosis." (PMID 32881863, 2020). "Mmp9 and Timp1 are known to be up-regulated in tuberculosis infection and have therefore been proposed as biomarkers for diagnosis of tuberculosis." (PMID 28542507, 2017). "MMP9 is highly expressed in human tuberculosis, in mouse models of tuberculosis and in M. marinum infection." (PMID 28747644, 2017). "The data supporting the inflammatory as well as pathological role of MMP-9 in tuberculosis reveals the possibility of its prominent therapeutic role." (PMID 27899068, 2016). "Studies have found generation of matrix-degrading phenotype in tuberculosis and implicate MMP-9 as key mediator in tuberculosis pathology." (PMID 27899068, 2016). "Matrix metalloproteinases in general can degrade most of the components of ECM and among MMP's, MMP-9 is suggested to have important role in the pathogenesis of the tuberculosis disease." (PMID 19290049, 2009). "Moreover, high expression levels of MMP-9 near caseous necrosis can promote tuberculosis progression by destroying the granulomatous structure." (PMID 36959923, 2023). "In malaria and tuberculosis MMP-9 was predominantly produced by activated monocytes." (PMID 25393535, 2014). "Inhibition of MMP-9 along with the TB treatment has shown increased bacillary clearance and inhibited inflammation in tuberculosis meningitis." (PMID 36776550, 2022). "We have previously shown MMP-9 expression in necrotic and cavitary lesions of M. tuberculosis-infected mice, with a corresponding decrease during TB treatment." (PMID 29758082, 2018). "Immunostaining demonstrated localization of MMP-9 primarily in macrophages in both murine and human lung tissues infected with M. tuberculosis, suggesting the importance of MMP-9 in TB pathogenesis." (PMID 29758082, 2018). "Therefore, in the current study we evaluated MMP-9 expression (utilizing immunohistochemistry) in M. tuberculosis-infected murine tissues as well as post-mortem specimens from TB patients." (PMID 29758082, 2018). "However, as MTB-infected monocytes or macrophages are proposed to be the major source of TNF-α and MMP-9 in tuberculosis, and there is emerging evidence that cell-cell interaction between immune cells and stromal cells are implicated the intercellular network to drive MMP production in tuberculosis." (PMID 26367274, 2015). "In addition, we propose CD14, IL-1R, THBS1, MMP9 and FYVE as potential biomarkers of bovine tuberculosis." (PMID 22815916, 2012). "In another study, also in an Ethiopian cohort of HIV co-infected TB patients, 7 genes (FCGR1A, RAB24, TLR1, TLR4, MMP9, NLRC4, and IL1B) accurately discriminated between active tuberculosis disease and latent infection." (PMID 33692804, 2021). "However, in our study MMP-9 concentrations did not change after initiation of tuberculosis treatment (plus corticosteroids) in patients with either TBM-IRIS or TBM-non-IRIS, and they increased significantly after ART initiation in the TBM-IRIS group." (PMID 25107295, 2014).